TBX15 (T-box transcription factor 15)
Description:
Probable transcriptional regulator involved in the development of the skeleton of the limb, vertebral column and head. Acts by controlling the number of mesenchymal precursor cells and chondrocytes (By similarity).
Synonyms: TBX14
Tractability: No criterion of Open Targets' tractability assessment is met for any kind of drug.
Gene: Protein-coding gene on chromosome 1 (118,883,046 to 118,989,556, reverse strand). Ensembl gene ENSG00000092607.
Subcellular location: Nucleus
Subcellular location (Human Protein Atlas): Nucleoplasm; Centrosome
Gene Ontology:
Molecular function: protein binding; sequence-specific double-stranded DNA binding; DNA-binding transcription factor activity, RNA polymerase II-specific; RNA polymerase II cis-regulatory region sequence-specific DNA binding; DNA-binding transcription factor activity; DNA-binding transcription repressor activity, RNA polymerase II-specific; protein homodimerization activity
Biological process: cell fate specification; regulation of transcription by RNA polymerase II; negative regulation of transcription by RNA polymerase II; positive regulation of DNA-templated transcription; regulation of DNA-templated transcription
Cellular component: chromatin; nucleus; RNA polymerase II transcription repressor complex
Genetic constraint (gnomAD): Loss-of-function variants: 18 observed, 56.63 expected, observed/expected ratio (o/e) 0.32, 90% interval 0.22 to 0.47. The upper end of that interval is the gene's LOEUF score, 0.47, which puts it in group 2 of 6, group 1 being the genes least tolerant of losing a copy. Missense variants: 692 observed, 782 expected, observed/expected ratio (o/e) 0.88, 90% interval 0.83 to 0.94. Synonymous variants: 295 observed, 292.34 expected, observed/expected ratio (o/e) 1.01, 90% interval 0.92 to 1.11.
Homologues: Orthologues: macaque TBX15 (100% identical), chimpanzee TBX15 (99% identical), dog TBX15 (99% identical), mouse Tbx15 (99% identical), guinea pig TBX15 (98% identical), rabbit TBX15 (98% identical), rat Tbx15 (98% identical), tropical clawed frog tbx15 (85% identical), zebrafish tbx15 (80% identical), Drosophila melanogaster mid (26% identical), Drosophila melanogaster H15 (25% identical), Drosophila melanogaster ocm (23% identical), and 8 more. Paralogues in human: TBX18 (56% identical), TBX22 (40% identical), TBX20 (30% identical), MGA (30% identical), TBX2 (25% identical), TBX3 (25% identical), TBX5 (25% identical), TBX1 (25% identical), TBX4 (25% identical), TBX6 (23% identical), TBX10 (22% identical), TBR1 (22% identical), and 4 more.
Diseases named in the same sentence as TBX15 in open-access papers:
TBX15 is named in the same sentence as 56 diseases in open-access papers, as found by Europe PMC text mining. Sharing a sentence is not in itself a finding about the gene and the disease. The quoted sentences say what the papers report.
Obesity (15 papers, 2013 to 2025). Accumulation of substantial excess body fat. "In humans, the expression of Tbx15 is associated with BMI and waist-to-hip ratio, reflecting levels of obesity and body fat distribution." (PMID 39308831, 2024). "Eight prioritised regulatory SNPs in the TBX15/WARS2 region are risk candidates for obesity and/or osteoporosis risk." (PMID 37139670, 2023). "In addition, our analyses showed upregulation of a novel obesity gene (TBX15) and a gene recently found associated to hepatic inflammation and apoptosis in mice (ZBTB33)." (PMID 40489530, 2025). "We showed a significant association between TBX15 methylation levels and obesity." (PMID 38971778, 2024). "Here, the authors identified signals of selection in Finns for a TBX15 missense variant associated with abdominal obesity and discovered that the obesity risk allele of this variant affects adipocyte expression of 13 genes in trans, including known thermogenesis genes." (PMID 39515300, 2024). "The ability of Tbx15 to regulate mitochondrial mass and activity, its high expression in glycolytic muscle, and the correlation of both polymorphisms and expression of Tbx15 to obesity lead us to hypothesize that Tbx15 might regulate metabolic function and fibre type in skeletal muscle." (PMID 26299309, 2015). "We suggest that TBX15 is a potential marker regulated by DNA methylation and related to obesity in IBC." (PMID 38971778, 2024). "Genome-wide association studies (GWAS) identified several variants of developmental regulatory genes that correlate with obesity, including in TBX15 and HOXC13." (PMID 39401200, 2024). "We suggest that TBX15 is a key gene regulated by DNA methylation that potentially contributes to obesity in IBC patients." (PMID 38971778, 2024). "We show that TBX15 is hypomethylated at multiple CpG sites in obesity and its expression is upregulated in hASCs and SAT from obese subjects." (PMID 30262812, 2019). "Overall, these results suggest a potential role for TBX15 in the mitochondrial and/or metabolic phenotype of mature adipocytes in an obesity context." (PMID 30262812, 2019). "Accordingly, it has been described that obesity can both increase and decrease TBX15 mRNA expression." (PMID 30262812, 2019). "Here we described for the first time that obesity down-regulates expression of TBX15 and HOXC10 in subcutaneous WAT resident stem cells." (PMID 24040759, 2013). "Noteworthy, TBX15 has been implicated in large European and smaller non-European GWAS studies for WHRadjBMI and other related obesity traits." (PMID 34340684, 2021). "Decreased expression of TBX15 is responsible for increased fat deposition, leading to obesity, but this gene may also be involved in insulin resistance." (PMID 30678306, 2019). "Moreover, contrasting reports have been published regarding depot-specific and obesity-dependent expression of TBX15, and its potential modulation of mitochondrial metabolism." (PMID 30262812, 2019). "Importantly, the TBX15 DMR overlaps with cis-regulatory elements, and the DMPs validated by BS-P are located close to the eight best candidates’ functional single nucleotide polymorphisms (SNPs) for obesity-trait or osteoporosis risk." (PMID 38971778, 2024). "Thus, Tbx15 has an important role in the regulation of glycolytic muscle development, and when it fails, this can lead to the development of metabolic syndrome phenotypes, including obesity, hepatosteatosis and glucose intolerance." (PMID 26299309, 2015). "Our study discovers a new key function for the TBX15 TF in trans regulating an adipose co-expression network of 347 adipose, mitochondrial, and metabolically important genes, including PPARG, KLF15, PPARA, ADIPOQ, and 35 obesity GWAS genes." (PMID 34340684, 2021). "Our study discovers a novel key function for the TBX15 TF in trans regulating an adipose co-expression network of 347 adipose, mitochondrial, and metabolically important genes, including PPARG, KLF15, PPARA, ADIPOQ, and 35 obesity GWAS genes." (PMID 34340684, 2021).
Obesity (continued). "We also demonstrate that the methylation status of TBX15, a transcription factor of the T-box family involved in adipogenesis, fat distribution and browning, might play an essential role in the mitochondrial phenotype of WAT in obesity." (PMID 30262812, 2019).
breast carcinoma (10 papers, 2015 to 2026). "The TBX15/miR-152/KIF2C pathway regulates adriamycin resistance in breast cancer by promoting PKM2 ubiquitination." (PMID 35456460, 2022). "Here we aimed to identify the effects and mechanisms of TBX15 in doxorubicin resistance in breast cancer." (PMID 34663310, 2021). "Among them, TBX15 levels were downregulated in breast cancer tissues, compared to normal adjacent tissues, and acted as a positive marker for the Relapse-Free survival prognosis of breast cancer." (PMID 34663310, 2021). "Our study showed that lower expression levels of TBX15 were detected in breast cancer tissues than normal tissues using TCGA database." (PMID 34663310, 2021). "Our studies demonstrate that TBX15/miR-152 pathway is downregulated in DOX-resistant breast cancer tissues and that KIF2C expression is induced by miR-152 suppression." (PMID 34663310, 2021). "We showed that TBX15 levels were correlated with miR-152 expression levels in breast cancer tissues using bioinformatics analysis." (PMID 34663310, 2021). "We found expression levels of TBX15 were downregulated in DOX-resistant breast cancer tissues, and were strongly correlated with miR-152 levels." (PMID 34663310, 2021). "The further study would be warranted to identify potential translation significance of TBX15 / miR-152 / KIF2C / PKM2 in clinical diagnosis or new treatment option for overcoming DOX resistance in breast cancer." (PMID 34663310, 2021). "TBX15 and miR-152 overexpression suppressed autophagy and glycolysis in breast cancer cells, while KIF2C overexpression reversed the process." (PMID 34663310, 2021). "Actually, TBX15 of breast cancer and cholangiocarcinoma were down-regulated compared to normal tissue as well as HCC, meanwhile this gene expressions of other cancer were up-regulated." (PMID 33447348, 2020). "TBX15 reduces PKM2 stability to mediate doxorubicin resistance in breast cancer." (PMID 38965548, 2024). "Our data identify a new mechanism by which TBX15 abolishes DOX chemoresistance in breast cancer, and suggest that TBX15/miR-152/KIF2C axis is a novel signaling pathway for mediating DOX resistance in breast cancer through regulating PKM2 ubiquitination and decreasing PKM2 stability." (PMID 34663310, 2021). "On the contrary, miR-152 inhibitor reversed TBX15-suppressed DOX resistance in breast cancer cells." (PMID 34663310, 2021). "We found TBX15 expression levels were decreased in Doxorubicin (DOX)-resistant breast cancer cells." (PMID 34663310, 2021). "Recently, the association of TBX15 and cancer was demonstrated by the detection of breast cancer tissue-specific down-regulation of TBX15, suggesting the use of TBX15 expression as a biomarker to facilitate accurate diagnosis and prognosis or as a predictive marker for treatment efficiency." (PMID 33447348, 2020). "TBX15 blocks autophagy and glycolysis in doxorubicin (DOX)-resistant breast cancer cells, thereby regulating PKM2 ubiquitination." (PMID 38965548, 2024). "Thus, we want to determine whether TBX15 may affect DOX resistance in breast cancer cells." (PMID 34663310, 2021). "To further investigate the effects of TBX15 expression on DOX sensitivity, we utilized two DOX-resistant breast cancer cell lines, MCF7/ADR, and T47D/ADR, and treated these cells with varying concentrations of DOX." (PMID 34663310, 2021). "Thus, TBX15/miR-152 pathway may play an important role in DOX resistance in breast cancer." (PMID 34663310, 2021). "However, role and mechanism of TBX15 in breast cancer chemoresistance is unknown." (PMID 34663310, 2021). "TBX15/miR-152 blocked autophagy and glycolysis in DOX-resistant breast cancer cells by targeting KIF2C." (PMID 34663310, 2021). "We induced T47D DOX-resistant breast cancer cells (T47D/ADR) by long exposure of DOX treatment in the cells, then detected its TBX15 expression level." (PMID 34663310, 2021). "However, role and mechanism of TBX15 in breast cancer is unknown." (PMID 34663310, 2021).
breast carcinoma (continued). "In addition, KIF2C was targeted by TBX15/miR-152, which inhibited autophagy and glycolysis in DOX-resistant breast cancer cells." (PMID 37328486, 2023). "TBX15 attenuation may result in miR-152 downregulation in DOX-resistant breast cancer cells, suggesting a potential new therapeutic target for breast cancer diagnosis and treatment in the future." (PMID 34663310, 2021). "Furthermore, we identified several unreported tissue-specific TFs that may contribute to breast cancer, including ATOH8, DMRT2, TBX15 and ZNF367." (PMID 28036274, 2017). "In addition, this study found the following tissue specific TFs that were not reported in breast cancer: ATOH8, DMRT2, TBX15 and ZNF367." (PMID 28036274, 2017).
Cousin syndrome (8 papers, 2010 to 2025). "More severe mutations in TBX15 are linked to Cousin syndrome and defects in craniofacial development." (PMID 39401200, 2024). "Mutations of TBX15 are associated with the congenital morphological abnormalities of patients with Cousin syndrome." (PMID 33447348, 2020). "In humans, the Cousin syndrome is characterized by craniofacial and skeletal defects with scapular and pelvic hipoplasia and is caused by TBX15 mutations." (PMID 27327083, 2016). "The Tbx15-deficient mouse, droopy ear, and engineered Tbx15-null mutants presented similar phenotype than the Cousin syndrome in addition to pigment pattern alterations." (PMID 27327083, 2016). "Nonetheless, the major phenotype of homozygous loss of function of TBX15 in humans (Cousin syndrome) or in mouse knock-out models is major deformities in the skeletal system reflecting a critical role for its encoded protein in embryonic skeletal bone formation." (PMID 36547252, 2022). "In digit formation specifically, Tbx3 is thought to modulate posterior digit identity through Shh and BMP signaling, and Tbx15 insufficiency causes Cousin Syndrome which includes congenital dwarfism, moderate brachydactyly (or shortening of the digits) and leg shortening." (PMID 21054883, 2010). "Cousin syndrome (MIM #260660) or pelviscapular dysplasia, is the result of bi‐allelic deleterious variants of the TBX15 gene and corresponds to a very rare constitutional bone disorder." (PMID 40673520, 2025).
ovarian carcinoma (8 papers, 2019 to 2024). A malignant neoplasm originating from the surface ovarian epithelium. "Gene prioritisation for WHR–endometriosis causal SNPs highlighted TBX15, an important mesodermal transcription factor with roles in endometrial and ovarian cancer." (PMID 35104295, 2022). "ZNF354C and TBX15 have been reported to be related to the occurrence of various cancers, including breast and ovarian cancer." (PMID 34824921, 2021). "TBX15 promoter methylation or lower TBX15 expression are found in ovarian cancer, pancreatic cancer, and hepatocellular carcinoma." (PMID 34663310, 2021). "Further, the TBX15 promoter is hypermethylated in histological subtypes of ovarian cancer, and the methylation levels and expression of TBX15 inversely correlate." (PMID 33447348, 2020). "Interestingly, low levels of TBX15 protein are usually expressed in prostate cancer and ovarian cancer, which may be related to hypermethylation in the promoter region of TBX158,17." (PMID 37328486, 2023). "Thus, hypermethylated TBX15 may serve as a potential biomarker for early detection of the induction and progression of ovarian cancer." (PMID 33447348, 2020). "Some hub genes (TBX15 and VCAN) are not well known, but have been reported to be highly expressed in many tumors in recent years, such as gliomas, ovarian cancer." (PMID 38520027, 2024). "Ovarian cancer detection from cervical scrapings is feasible, using particularly promising epigenetic biomarkers such as AMPD3/NRN1/TBX15." (PMID 31775891, 2019).
prostate carcinoma (8 papers, 2015 to 2023). A carcinoma that arises from epithelial cells of the prostate gland. "For example, TBX15 is a methylation marker of prostate cancer associated with advanced stage and ETS-related gene (ERG) expression, which regulates cell proliferation, angiogenesis, and apoptosis." (PMID 33447348, 2020). "TBX15 is a T-box transcription factor essential for development, also proposed as a marker in prostate cancer; and, recently, its antiapoptotic function indicates a role in carcinogenesis." (PMID 27327083, 2016). "One study carried out in human placentas, indicated that PDX1 regulates TBX15 in a methylation-dependent manner; and methylation of TBX15 has also been proposed as a prognostic marker for prostate cancer." (PMID 27327083, 2016). "Previous reports have shown that TBX15 expression can be used as a prognostic marker for HCC, and HBB has been reported to play a key role in prostate cancer differentiation and in a variety of important biological pathways (e.g., iron metabolism)." (PMID 34458266, 2021). "Further, a combination of TBX15 and other hypermethylated genes is a useful biomarker for ERG expression and recurrence of prostate cancer." (PMID 33447348, 2020).
Abdominal obesity (5 papers, 2021 to 2025). Excessive fat around the stomach and abdomen. "The first one, T-Box Transcription Factor 15 (TBX15) was just recently identified as a novel “adipose master trans regulator of abdominal obesity genes” in a gene wise association study (GWAS) for polygenic risk for abdominal obesity and T2D in the UK biobank." (PMID 40489530, 2025). "We hypothesize that the signatures of selection are due to the role of TBX15 in thermogenesis, i.e., in populations residing in climates similar to Finland, the abdominal obesity risk allele T of rs10494217 also has the potential to be selected for." (PMID 39515300, 2024). "In the present study, we focus our analysis on an abdominal obesity GWAS missense variant, rs10494217, in a unique adipocyte marker and a known mouse thermogenesis gene, TBX15,14,12,13 to explore its role in adipocyte expression in the context of abdominal obesity." (PMID 39515300, 2024). "Thermogenesis dissipates energy as heat, burning fat and leading to a rise in core body temperature, and here we hypothesized that the rs10494217 abdominal obesity risk allele T of TBX15 increases body fat to provide more insulation and fuel to thermogenesis and cold resistance." (PMID 39515300, 2024). "After discovering that heritability of abdominal obesity is enriched in adipocytes, we focused on a SAT unique adipocyte marker gene, the transcription factor TBX15, and its abdominal obesity-associated deleterious missense variant, rs10494217." (PMID 39515300, 2024). "In addition, our previous paper in humans has identified a SAT co-expression network correlated with abdominal obesity and regulated by TBX15 using bulk RNA-seq analysis followed by siRNA knockdown experiments." (PMID 39515300, 2024). "Thus, based on our converging genomic, transcriptional, and functional evidence, we interpret the role of TBX15 to be a main transcriptional regulator in the adipose tissue and discover its importance in human abdominal obesity." (PMID 34340684, 2021). "We found only one missense variant residing in the T-Box Transcription Factor 15 (TBX15) gene, a unique adipocyte marker gene that encodes a transcription factor (TF) that has been shown to regulate a SAT bulk co-expression network associated with abdominal obesity." (PMID 39515300, 2024). "Intriguingly, we found that TBX15, which is a unique adipocyte marker gene in the snRNA-seq data both from KOBS and RYSA, contained one common missense abdominal obesity GWAS SNP, rs10494217." (PMID 39515300, 2024). "Additionally, we analyzed TBX15 at a single-cell resolution, focusing on the adipocyte cell type, as we observed that it is the relevant SAT cell type for the heritability of abdominal obesity in obese cohorts." (PMID 39515300, 2024).